CD4 (CD4 molecule)
Diseases named in the same sentence as CD4 in open-access papers (continued):
Sharing a sentence is not in itself a finding about the gene and the disease.
AIDS (continued). "Additionally, Missed Appointments and Appointments Missed or Infrequent were negatively associated with CD4 cell count >500 cells/mm3 and positively associated with ART initiation, progression to AIDS, hospital admission, and ED visits." (PMID 25794182, 2015). "Cox regression analysis revealed that several factors, including age at diagnosis, transmission routes, census register, year of diagnosis, baseline CD4+ T-cell count and CD4+ T-cell count of initial HAART played significant influence roles in the progression of HIV to AIDS." (PMID 26413133, 2015). "In adult HIV infection, immune activation levels predict disease outcome better than viral load, and CD4 decline to AIDS can be observed in elite controllers (whose viral load is undetectable) as a result of the strong correlation between absolute CD4 count and immune activation." (PMID 26834742, 2015). "In Phidisa, there were relatively few serious non-AIDS events, but with consideration of any grade 4 event, like EuroSIDA, CD4+ risk gradients were not as large as for AIDS." (PMID 25856495, 2015). "A CD4 count at AIDS diagnosis below 50 cells/mm3 was more frequently observed among PWA who acquired HIV infection through heterosexual intercourse (50.1 %), or homosexual male intercourse (42.3 %) than among injecting drug users (33.8 %) (Chi-square test, p < 0.01)." (PMID 26067992, 2015). "Primary endpoints were VL<3000 copies/mL and CD4 cells >500 cells/mm3 at 48 weeks; secondary endpoints were immune activation, inflammatory markers until 48 weeks and the time before resuming ART (CD4 <350 cells/mm3 or AIDS) after ‘final stop’, compared between groups." (PMID 26186440, 2015). "An initial CD4 count <350 cells/μl or an AIDS-defining illness defined late presentation." (PMID 26584954, 2015). "Oral candidiasis is a predictor of reduction in CD4+ and AIDS progression." (PMID 25745611, 2015). "Overall, women in the cohort tended to have less time between the diagnoses of HIV and AIDS, lower minimum CD4 cell counts and percents, and higher maximum HIV viral loads compared to men, although only the difference in CD4 cell count was statistically significant." (PMID 26107253, 2015). "However, different criteria have been used to define late presentation among HIV infected individuals, which generally include CD4 cell count and/or AIDS-defining diseases." (PMID 26412578, 2015). "Despite a lack of AIDS-defining illnesses or deaths in this cohort, SIVcpz infection was associated with significant depletion of CD4+ T-cells." (PMID 26360709, 2015). "A positive correlation between CD4+ T-cell decline and infection by syncytium-inducing HIV-1 or SIV-1 variants has been established in vitro and, more importantly, in vivo, in humans with AIDS." (PMID 26247731, 2015). "CD4+ T-cell levels partially recover after this phase; however, they gradually decline as the infection progresses, ultimately contributing to the development of acquired immunodeficiency syndrome (AIDS)." (PMID 26441989, 2015). "In conclusion, our study demonstrates that MVA-B is a broadly immunogenic HIV/AIDS vaccine candidate that stimulated polyfunctional HIV-specific CD4 T cell responses with a T effector memory (TEM) phenotype in HIV-1-infected patients on HAART, and also enhances vector-specific CD8 T cell responses." (PMID 26544853, 2015). "This differential sensitivity has been proposed as one mechanism for the increased sensitivity to TMP-SMX in HIV infected individuals: as the HIV infection progresses to AIDS, the relative depletion of CD4+ cells yields CD8+ cell predominance and an overall diminished reduction capacity." (PMID 26798528, 2015). "This hypothesis is also strengthened by the comparison of our results with previous data from the SHCS: between 1998 and 2007, 31% of patients presented with CD4 <200 cells/μl and/or AIDS, whereas this proportion was 19% during our study period (2009 to 2012)." (PMID 26584954, 2015).
AIDS (continued). "We excluded individuals with CD4 cell count below 200/μL and/or a current or previous AIDS event at HIV diagnosis, as these individuals are likely to start cART rapidly in France, irrespective of their administrative status, financial resources and healthcare coverage." (PMID 25734445, 2015). "Elevated risks of early mortality were associated to older age (OR = 5.28; 95 % CI: 4.41-6.32 for age ≥60 vs. <35 years), injecting drug use (OR = 1.71; 95 % CI: 1.53-1.91 vs. heterosexual intercourse), and CD4 count <50 cells/mm3 at AIDS diagnosis (OR = 1.87, 95 % CI: 1.55-2.27 vs. ≥350)." (PMID 26067992, 2015). "Cox proportional hazards regression was performed to determine the relative contribution of each factor (i.e., demographic characteristics, mobility, transmission routes, year of diagnosis, treatment with HAART and CD4+ T-cell count at baseline) to the progression of HIV of AIDS." (PMID 26413133, 2015). "This profile associated with lower accumulation of naive CD4 T cells is a hallmark of non-progression to AIDS." (PMID 26640894, 2015). "Response to treatment for GTN is generally favourable; but the sequelae of HIV and/or AIDS, the resultant low CD4 counts, comorbidities, poor performance status and the extent of metastatic disease in patients receiving chemotherapy, compromise the prognosis and survival." (PMID 29568578, 2015). "We have found that even when helper CD4 T cells are profoundly reduced in a mouse model that mimics this defect in AIDS, other remaining T cells are capable of mounting vaccine immunity against a deadly fungal infection, and they do so by producing the powerful, soluble product, IL-17." (PMID 26367276, 2015). "Furthermore, as a primary target of HIV infection, the decline of CD4+ cells used as a biomarker of progression to AIDS in HIV infected individuals." (PMID 26415705, 2015). "Our finding that AA was inversely associated with CRP and triglycerides and positively associated with HDL-C, CD4+ cell count and plasma albumin suggests that individual fatty acids may influence clinical outcomes in HIV/AIDS patients." (PMID 26161268, 2015). "Their median nadir CD4 cell count was 195 cells/mm3, and 55% had a prior diagnosis of AIDS." (PMID 26642314, 2015). "A simple example shows that the parameters seem to correspond as we would expect: take μ = 1/40, Tj = 4 years (i.e. time to reaching ‘low CD4’ treatment threshold), dj = 1 per year (i.e. AIDS-related death rate), then the calculations give pj ≈ 9/40 and aj ≈ 9/50." (PMID 26609066, 2015). "Their median nadir CD4 cell count was below 200 and most had a diagnosis of AIDS." (PMID 25394151, 2014). "While safety and indication of biological effect in HIV-infected individuals have been observed for delivery to CD4+T cells and to CD34+ HSC, the clinical impact of each cellular target in terms of long-term preservation of total CD4+T cell counts and forestalment of AIDS remains uncertain." (PMID 24945407, 2014). "Our findings show high rates for TB as a new AIDS diagnosis among those with poor CD4 recovery." (PMID 24594114, 2014). "Plasma HIV-1 tropism does not appear to add to the ability of CD4 count and viral load to predict the short term risk of AIDS and death outcomes, even with 454 sequencing." (PMID 25397435, 2014). "A decline of CD4+ T cells below 200 per μl of blood defines AIDS." (PMID 25226169, 2014). "Viral load was removed from DHHS recommendations in 2007, because of data indicating that risk of AIDS or death in individuals receiving cART with pre-treatment CD4 counts ≥350 cells/μL was <2% regardless of viral load." (PMID 24830290, 2014). "The proportion of patients presenting with advanced HIV disease (CD4 count<200/mm3 or presenting with an AIDS-defining event) was 30.6%; and 52.4% of patients were late presenters (CD4 count<350/mm3 or presenting with an AIDS-defining event)." (PMID 25397428, 2014).
AIDS (continued). "However, male gender, age between 35–49, previous AIDS event, lower CD4+cell count at diagnosis and lower nadir CD4+ T-cell count were associated with mortality after Hodgkin lymphoma." (PMID 24760049, 2014). "Similarly, a study from a tertiary level Mexico City hospital categorized 61% of people as late-testers because within six months of diagnosis, they had CD4 counts below 200 and/or they had experienced an AIDS-defining illness." (PMID 25372464, 2014). "CD4 at death was lowest for those who died of AIDS-related causes (median, 48 [IQR, 13–140], due partly to the use of CD4 in assigning causes of death), and highest for those who died of CVD (median, 360 [IQR, 221–608]) and unnatural causes (median, 340 [IQR, 150–560])." (PMID 24771333, 2014). "The mean CD4 counts in patients with AIDS were 150 cells/μl (ranging from 77 to 200 cells/μl) and each of the studied patients fulfilled the criteria of AIDS according to the CDC." (PMID 24896832, 2014). "These patients also had been diagnosed with HIV for a longer time, with a median time of 117.7 (IQR 50.7–158.7) vs. 77.1 (IQR 28.9–134.2) months, and they were more likely to have an AIDS diagnosis (52.7% vs. 42.4%) and a current CD4+ count below 350 cells/mm3 (50.7% vs. 31.2%)." (PMID 24699873, 2014). "In Kaplan–Meier analysis, the risk of developing new AIDS condition was much higher among those with poor CD4 recovery regardless of the definition used." (PMID 24594114, 2014). "In general, HIV-infected adults are more likely to develop clinical malaria and this risk becomes more pronounced with advancing immunosuppression such that at CD4 T-cell count below 200 cells/μL (AIDS) individuals will experience increased incidence of malaria infection." (PMID 24729787, 2014). "Bleomycin/vincristine for the treatment of AIDS-associated KS was associated with better tumor response compared to vincristine monotherapy without impairing CD4 count recovery." (PMID 24632813, 2014). "A separate review of the 20 busiest HIV/AIDS clinic sites referring the highest number of CD4 samples per day, revealed that eleven of these sites had immediate on-site access to a laboratory CD4 testing facility, with the remaining nine were in very close (5 km) radius of a testing facility." (PMID 25490718, 2014). "The surrogate markers of HIV/AIDS progression include CD4 T cell count and plasma viral load." (PMID 24828336, 2014). "After adjustment for prior ARV exposure, comorbidities, AIDS-defining events, sex, age, and health plan type, patients with CD4 cell counts <100 cells/μL had significantly higher (92% increased; p<0.001) costs per person-month as compared to those with CD4 cell counts >350 cells/μL." (PMID 24866200, 2014). "Median time of HIV was 201.7 months, CD4+ nadir was 268 cells/mm3, and 75% had previous AIDS." (PMID 25394095, 2014). "High CD4 cell counts were associated with a lower incidence rate of AIDS and non-AIDS events as well as with lower rates of specific non-AIDS events, such as bacterial, hepatic, viral, neurological, and cardiovascular conditions." (PMID 24885790, 2014). "IFN-γ levels found in these patients may be due a global decrease of CD4+ T cells in CT/AIDS and a possible central tolerance to parasite antigens in those patients with ocular toxoplasmosis." (PMID 25352834, 2014). "Baseline CD4 was also strongly inversely associated with AIDS, non-AIDS infection, and liver-related mortality after the first year of ART, although the association with non-AIDS malignancy was attenuated compared with the first year." (PMID 24771333, 2014). "CD4 at 12 months was strongly inversely associated with subsequent rates of AIDS mortality, and also inversely associated with non-AIDS malignancy, non-AIDS infection, and liver-related death." (PMID 24771333, 2014).
AIDS (continued). "A recent population-based cohort study investigated 5,160 AIDS patients in four of the five Brazilian regions from 2003 to 2010 and found that 53.4% of patients started treatment with CD4+ counts lower than 200 cells/mm3, which is close to that seen in our study." (PMID 25398533, 2014). "Among 24107 HIV-infected adults enrolled in the International epidemiological Database to Evaluate AIDS (IeDEA) Collaboration in the West African region, a significantly higher mean CD4 gain was observed among younger patients when compared to elderly patients after 12 months of cART initiation." (PMID 24586673, 2014). "In our view, this particular population of immunological responders with low CD4/CD8 ratio –hence, very high CD8+ T-cells– could represent a clinical phenotype of immunological responders at higher risk for non-AIDS-associated morbidity and mortality." (PMID 24497929, 2014). "Low CD4/CD8 ratio is associated with a high risk of AIDS and non-AIDS events and may act as a marker of immune senescence." (PMID 25393989, 2014). "Of them, 50.5% were late presenters (AIDS defining illness or <350 cells/μl total CD4 count)." (PMID 25436642, 2014). "Factors investigated included: gender, mode of HIV transmission, time from HIV diagnosis, CD4 count, nation of birth, AIDS, HCV-status, age, CD8 count, VL, diabetes, smoking, total and HDL cholesterol, eGFR, blood glucose, level of education and employment and site location." (PMID 25397519, 2014). "The authors of a study conducted in Sao Paulo argued that it might be due to lower access to HAART and lower CD4+ counts at AIDS diagnosis." (PMID 25398533, 2014). "Indeed, and perhaps as a consequence of the fact that CD4-depletion resulted in very high virus replication, seven of the eight depleted RMs had to be euthanized for AIDS-related reasons briefly after ART initiation." (PMID 25356757, 2014). "Predictors of AIDS defining tumours at the time of data collection were: male sex (57.9% vs 40.6%, p=0.004), CD4 T-cell counts <200 c/mmc (63.6% vs 44.1%, p<0.0001), whereas being cART treated at the time of tumour diagnosis was protective (38.0% vs 68.0%, p<0.0001)." (PMID 25394156, 2014). "In SMART and ESPRIT, HIV-positive participants taking suppressive cART with high CD4+ cell counts were followed for several years and fatal and non-fatal AIDS, SNA and other causes of deaths were centrally adjudicated against standard event criteria." (PMID 24728071, 2014). "CD4+ T-cell count thresholds for treatment initiation have increased over time and newer first-, second- and salvage-line antiretroviral drugs with greater efficacy and lower toxicity profiles have been introduced within the National AIDS Program." (PMID 24919778, 2014). "In the United Kingdom, Collaborative HIV Cohort Study, sub-optimal CD4 increases were associated with an increased risk of death but not with new AIDS events." (PMID 24594114, 2014). "Of importance, since the CD4/CD8 ratio is available in routine clinical practice, its use as a predictor of non-AIDS associated morbidity and mortality might be easily implemented in clinical settings." (PMID 24497929, 2014). "The aim of our study was to evaluate whether anti-Nef antibodies were involved in paediatric AIDS development and whether they can prevent the CD4+ T-cell depletion in vertically infected children." (PMID 24560340, 2014). "Therefore, our finding on the augmentation of host innate and humoral immunity against tumors by maspin is relevant to the development of immunotherapeutic strategies for cancer patients with CD4+ T cell defects, such as AIDS patients." (PMID 25373490, 2014). "Also these studies observed that patients with AIDS and low CD4 cell counts mounted allergen-specific IgE responses in serum but they have not considered interpreting these findings regarding T cell dependence of IgE production." (PMID 24896832, 2014).
AIDS (continued). "Albeit the magnitude of the association was smaller, lower CD4 cell counts were also associated with a higher incidence rate of non-AIDS events, of specific non-AIDS events, and of deaths." (PMID 24885790, 2014). "In conclusion, patients with immuno-virological discordance, in the context of suppressed viral load appeared to be at higher risk of fatal and non-fatal non-AIDS events although most of this increased risk seems to be explained by a low current CD4 count." (PMID 24498036, 2014). "The impact of use of POC technologies (like CD4 testing) in a HIV/AIDS programmatic context to improve newly diagnosed HIV+ patient's enrolment onto treatment and retention in care is an important from a perspective of retaining patients in care, but beyond the scope of this study." (PMID 25517412, 2014). "In addition to progressive reduction of CD4+ T cells, peripheral blood cytopenias, such as anaemia, neutropenia and thrombocytopenia, happen in most patients with AIDS." (PMID 24387326, 2014). "Additionally, advanced HIV disease (AD) is defined by a CD4 count below 200 cell/mm3 or an AIDS defining condition in persons presenting to care." (PMID 25397438, 2014). "Matching criteria included time HIV+ or since AIDS diagnosis, age, race and CD4+ cell count." (PMID 24922518, 2014). "Consequently, this pathway has been identified as a possible mechanism that contributes to apoptosis of CD4 T cells in AIDS." (PMID 25196285, 2014). "Excessive immune activation in the subpopulation of HIV-2 patients with viremia may explain why they develop AIDS or die at relatively high CD4 counts." (PMID 24803534, 2014). "The results of this study indicated increased levels of CD4 over time in a cohort of patients living with HIV/AIDS and identified factors that may influence this increase and are liable to intervention." (PMID 24505247, 2014). "HIV-infected patients generally presented with advanced AIDS (median CD4 cell count 58 cells/μl)." (PMID 24608875, 2014). "AIDS was first clinically observed from the US Centers for Disease Control in 1981, which is now defined as either a CD4+T-cell count below about 200 per microlitre blood, or the occurrence of specific diseases in association with certain HIV-related conditions and symptoms." (PMID 24963975, 2014). "LP was defined in Collaboration of Observational HIV Epidemiological Research Europe (COHERE) as HIV diagnosis with a CD4 count <350/mm3 or an AIDS diagnosis within 6 months of HIV diagnosis among persons presenting for care between 1 January 2000 and 30 June 2011." (PMID 24137103, 2013). "Among the 41 SHIV with an AIDS diagnosis or CD4 <350 at OB entry, only 14/41 (34%) were on HAART." (PMID 24106419, 2013). "We examined the predictors of CD4:CD8 normalization after combination antiretroviral therapy (cART) and determined whether normalization is associated with reduced progression to AIDS-defining illnesses (ADI) and death." (PMID 24204912, 2013). "SAMHD1-mediated HIV-1 restriction in resting CD4+ T-lymphocytes might be important for AIDS immunopathogenesis." (PMID 24523981, 2013). "32.87% AIDS patients had very low CD4+ T-cell counts at AIDS diagnosis (<50 cells/μL)." (PMID 24376638, 2013). "Cohorts of PWID in other countries have reported similar findings: PWID were more likely to have lower nadir CD4 cell count measurements, present with AIDS defining illnesses, have higher rates of active TB, have higher prevalence of hepatitis/HIV co-infections, and receive HIV diagnosis late." (PMID 23457477, 2013). "In agreement with studies in industrialized countries, these findings indicate that the percentage of CD4 cells in children with HIV/AIDS (i.e. the immunologic category) could be used to guide treatment initiation." (PMID 23280237, 2013). "Patients with HIV/AIDS are typically at low risk of IA as immune defect is in CD4 cells which do not appear to play an important role in combating aspergillosis; however, cases of IA in AIDS have been reported." (PMID 24278780, 2013).